HLA-E (major histocompatibility complex, class I, E)
Diseases named in the same sentence as HLA-E in open-access papers (continued):
Sharing a sentence is not in itself a finding about the gene and the disease.
tumor (continued). "HLA-E protein levels are generally higher in tumor cells than in healthy tissues and available evidence indicates that IFNγ can upregulate HLA-E expression." (PMID 39706891, 2025). "This increased IFN-γ signaling in the tumor microenvironment induces overexpression of HLA-E and PD-L1 by cancer cells, NKG2A on CD8 T cells and natural killer (NK) cells, as well as PD-1 on CD8 T cells." (PMID 41228348, 2025). "The effectiveness of NK-based responses is reduced when tumor cells express HLA-E, which engages the inhibitory NK receptor NKG2A." (PMID 41322778, 2025). "NKG2A is a key inhibitory receptor for NK cells, and HLA-E is highly expressed on a wide range of tumours compared to healthy cells." (PMID 40291981, 2025). "Even outside the transplant setting, CMV seropositivity has been associated with enhanced NK cytotoxicity against hematologic targets, with activity modulated by tumor HLA-E and donor NK phenotype." (PMID 41322778, 2025). "This receptor’s ligand is the HLA-E molecule, which is expressed in high numbers by some tumor cells in order to evade the immune system’s surveillance." (PMID 41369346, 2025). "Their spatial colocalization with PD‐L1+/HLA‐E+ tumor microdomains reveals a coordinated immune evasion strategy." (PMID 40877861, 2025). "Activation of anti-tumor immune response by effector CD8+ T-cells and increased IFNγ levels have been shown to promote the expression of HLA-E, the human orthologue of mouse Qa-1b, in tumor cells." (PMID 39706891, 2025). "CRISPR-mediated KLRC1 gene editing not only targets the NKG2A/HLA-E IC but also enhances NK cell cytotoxic responses against HLA-E-positive tumor cells by augmenting NKG2C function." (PMID 40463500, 2025). "Although it is frequently prevalent in trophoblast and tumor cells, HLA-E can be expressed at low levels in all nucleated cells." (PMID 40066089, 2025). "HLA-E is normally expressed at low levels, but its expression increases on the surface of most tumor cells, thereby inducing a cascade of inhibitory signals that hinder NK cytotoxic activity and cytokine secretion." (PMID 40370819, 2025). "Tumor cells not only upregulated the expression of surface HLA-E but also a soluble form that can circulate in the environment and potentially bind NKG2A on NK cells and suppress their activity." (PMID 41440003, 2025). "Spatial and molecular profiling revealed that these cells localize within PD-L1+/HLA-E+ tumor niches, suggesting that immune suppression is spatially and molecularly coordinated." (PMID 40877861, 2025). "Circulating tumour cells that express HLA-E can escape NK-cell-mediated immune surveillance by engaging the heterodimer CD94-NKG2A51." (PMID 39984653, 2025). "Tumor cells suppress NK cells cytotoxicity through upregulation of HLA-E and PD-L1, which interact with inhibitory receptors NKG2A and PD-1 on NK cells." (PMID 41562080, 2025). "This analysis confirmed the widespread co-expression of PD-L1 and HLA-E directly on CK7+ epithelial cancer cells within the tumor tissue." (PMID 40877861, 2025). "On the other hand, induced hyperthermia upregulates HLA-E expression by tumor cells, which stimulates the inhibitory NK surface signal CD94." (PMID 41375025, 2025). "Critically, we identified tumor cells co-expressing CK7, HLA-E, and PD-L1, confirming the presence of immunosuppressive ligands within the epithelial tumor compartment." (PMID 40877861, 2025). "This study employed multiplex immunofluorescence assays to investigate the association between NK cell proportion, HLA-E levels, and both cumulative incidence of recurrence (CIR) and cumulative incidence of tumor-related death (CID) in ESCC patients." (PMID 39845968, 2024). "As antibody specificity for isolation of pHLA-E and MS instrumentation sensitivity continue to improve, there is considerable potential for high-throughput discovery and validation of HLA-E viral epitopes and tumor antigens." (PMID 39301027, 2024).
tumor (continued). "Generally, HLA-E is expressed in dendritic cells, tumor cells, macrophages, and other nucleated cells within tumor nests." (PMID 39845968, 2024). "Here, we identified HLA‐E as a downstream target gene of IRF5 and demonstrated that the overexpression of HLA‐E can counteract the tumor‐promoting effects induced by si‐IRF5 M1‐exos." (PMID 39623605, 2024). "In this study, the level of HLA-E expression in ESCC tumor nests was quantified, and immunoreactivity scores (IRS) were assessed." (PMID 39845968, 2024). "The expression of the HLA-E protein is enriched on the surfaces of unhealthy cells, such as infected cells as well as tumor and senescent cells." (PMID 38954358, 2024). "We assessed AYA22T-aptamers’ binding specificity to NKG2A on NK cells, aiming to enhance NK cell-mediated tumor lysis by disrupting NKG2A interactions with the HLA-E axis." (PMID 38473398, 2024). "The HLA-E-NKG2A axis is an emerging immune checkpoint that restrains anti-tumor immune responses and high HLA-E expression correlates with a T cell inflamed microenvironment." (PMID 38418901, 2024). "NKG2A is expressed in nearly 50% of NK cells in peripheral blood, while HLA-E expression is low in normal tissue cells but elevated in tumor-infiltrating NK cells, CD8+ T cells, and tumor cells." (PMID 39221244, 2024). "In this review, we will discuss the direct and indirect impacts of GMMs on the activity of effective CD8 and NK cells and on the expression of CD94/NKG2A in the immune cells and/or their ligand HLA-E in the tumor cells." (PMID 39229258, 2024). "The expression of HLA-E in NSCLC has also been found to restrain the positive prognostic effect of stromal CD8+ tumor-infiltrating T cells, highlighting its complex role in immune modulation within the TME." (PMID 39766165, 2024). "The immunosuppression score (ISS), derived from NK cell proportion and HLA-E expression, proved to be a more robust predictor of recurrence and tumor-related mortality compared to NK cell status or HLA-E levels alone." (PMID 39845968, 2024). "GMMs such as Trp metabolites, BA metabolites and SCFAs have widely effects on the function and differentiation of immune cells such as CD8 and NK cells, which are involved in NKG2A: HLA-E ICB immunotherapy against tumor." (PMID 39229258, 2024). "There is clear evidence that the NKG2A/HLA-E complex inhibits the immune surveillance and impairs the clearance of tumor cells by the cytotoxic NK and CD8+ T cells." (PMID 38954358, 2024). "High levels of IFN-γ can lead to an upregulation of HLA-E on tumor cells, which has also been observed following CAR33-NK cell therapy in AML-bearing mice as well as in CAR33-KLRC1ko-NK cells following AML cell contact in vitro 19,46." (PMID 39349459, 2024). "In this review, we will discuss the impacts of GMMs and GMM educated immune cells on the activity of effective CD8 and NK cells and the expression of CD94/NKG2A in immune cells and/or their ligand HLA-E in tumor cells." (PMID 39229258, 2024). "further showed that the availability of free β2‐microglobulin in tumor cells, especially those with HLA‐class Ia downregulation, is correlated with HLA‐E expression." (PMID 38882209, 2024). "In this study, a computational biology approach was employed to engineer a series of enriched aptamers targeting CTLA-4 and NKG2A receptors on CD8+ T cells and NKG2A receptors on NK cells interactions with B7-1/B7-2 and HLA-E on tumor cells." (PMID 38473398, 2024). "The expression of HLA-E, along with the increased levels of CD94/NKG2A observed in tumor-infiltrating lymphocytes (TILs), has been associated with tumor progression, metastasis, and decreased patient survival rates in certain cancers." (PMID 39584993, 2024). "In the field of cancer immunotherapy, HLA‐E exhibits high expression levels in various tumors, and its expression level correlates with the prognosis of tumor patients, depending on the tumor type." (PMID 39623605, 2024).
tumor (continued). "Recently, studies have shown that both inorganic and organic selenite are available to down-regulate the expression of HLA-E in tumor cells but activate NK cells." (PMID 39065636, 2024). "Collectively, the high PEX HLA-E mRNA expression appears to reflect the high HLA-E mRNA transcription and protein translation in the corresponding tumor." (PMID 39867897, 2024). "All of these findings point to the complexity of HLA‐E upregulation as a process that is impacted by cellular stress, tumor cell properties, and viral infection." (PMID 38882209, 2024). "The expression of HLA-E molecules on the tumor cell surface was upregulated to escape the immune surveillance of NK cells." (PMID 39611150, 2024). "Interrupting this interaction by blocking NKG2A or downregulating HLA-E expression enhances NK-mediated tumor cell eradication in vitro and prevents tumor metastasis in vivo." (PMID 39090094, 2024). "Due to their non-polymorphic nature, the literature has mentioned both NKG2A/CD94 and HLA-E as potential therapeutic targets to enhance NK cell anti-tumor-killing efficacy." (PMID 39339180, 2024). "The overexpression of HLA‐E in tumor cells, TAMs, and dendritic cells has the potential to hinder the immune response against tumors by restricting NKG2A+CD8+lymphocytes from infiltrating the TME." (PMID 39623605, 2024). "The interaction between NKG2A and human leukocyte antigen‐E (HLA‐E) serves to inhibit the activation of NK cells and T cells, and interrupting this interaction has been shown to enhance tumor immune response." (PMID 39540362, 2024). "Immune checkpoint inhibitors such as HLA-E: NKG2a blockages are effective immunotherapy strategies against tumor." (PMID 39229258, 2024). "Of late, the NKG2A axis, a novel immune checkpoint interacting with HLA-E on tumor cells, has been identified." (PMID 38473398, 2024). "HLA-E is found to be upregulated on tumor cells due to IFN-γ response genes located upstream on the HLA-E gene when immune effector cells reach the site of infection and secrete IFN-γ." (PMID 39273395, 2024). "HLA-E has been reported to be upregulated in many tumor types and promotes NK cell self-tolerance, leading to tumor evasion." (PMID 38256021, 2024). "NK cells are under constitutive inhibition by inhibitory receptors for MHC class I, and genome-scale CRISPR-based gene editing screens have revealed that HLA-E interactions with NKG2A are a key determinant for tumour cell sensitivity to NK-cell mediated lysis." (PMID 38223411, 2024). "NKG2A acts as an inhibitory checkpoint receptor, and blocking the NKG2A/HLA-E axis has been shown to enhance anti-tumor immune responses by increasing NK cell activity." (PMID 39845968, 2024). "This also blocks the NKG2A ligand, HLA-E, which is overexpressed in the human tumor microenvironment (TME) and which reduces lymphocyte expression in the TME." (PMID 36829496, 2023). "(iv) Selenium-containing nano-biomaterials inhibit the expression of human leukocyte antigen E (HLA-E) on cancer cells to enhance the anti-tumor immunity mediated by NK cells, opening up a new approach for cancer radio-immunotherapy." (PMID 37899463, 2023). "In summary, we demonstrated that high HLA-E expression can be evaluated as a sex-independent marker for survival in patients with OSCC and is associated with advanced tumor stage." (PMID 38069020, 2023). "In terms of HLA expression, HLA-A, HLA-B, HLA-C, HLA-E, HLA-F, HLA-G, and HLA-J were significantly more highly expressed in C2 than in C1, indicating that tumour subtypes differ in the activation of immune cells." (PMID 37691922, 2023). "IFN-γ, secreted in the TME, promotes HLA-E expression on the tumor cell surface, which binds its specific receptor NKG2A, a major NK inhibitory receptor, encoded by the KLRC1 gene." (PMID 37675109, 2023).
tumor (continued). "HLA-E is also recognised by the activating receptor NKG2C expressed on NK cells and interestingly, NKG2C + NK cells are reduced in CLL patients, with high expression of HLA-E detected on tumour cells." (PMID 37528310, 2023). "In vivo, the adoptive transfer of human KLRC1KO NK cells significantly delayed tumor progression and increased survival in a xenogeneic mouse model of HLA-E+ metastatic breast cancer, as compared to WT NK cells (p = 0.0015)." (PMID 37675109, 2023). "This interaction between NKG2A and HLA-E contributes to tumor immune escape; therefore, NKG2A-mediated mechanisms are currently being exploited to develop potential anti-tumor therapeutic strategies." (PMID 36831606, 2023). "The high levels of cell surface HLA-E expression contributed to the tumor escape from immune surveillance, through inhibiting NK lysis." (PMID 38007483, 2023). "HGSC patients with a high fraction of intratumoral CD3+ T lymphocytes had longer progression-free survival (PFS) as well as high HLA-E expression on tumor cells, along with an HRD profile which showed improved overall survival." (PMID 38067396, 2023). "In preclinical studies, blocking the NKG2A receptor with a targeted antibody has been shown to restore the capacity of Vδ2pos T cells even against HLA-E+ tumor cells." (PMID 37371767, 2023). "The expression of class I HLA molecules, which are responsible for antigen presentation to tumor-killing T-cells, including HLA-A, HLA-B, HLA-C, HLA-E, HLA-F, and B2M, was downregulated in 7, 8, 5, 10, 5, and 14 patients, respectively." (PMID 37152992, 2023). "In present study, we showed that IFN-γ-induced HLA-E upregulation would decrease NK lysis to tumor cells." (PMID 38007483, 2023). "In fact, masking with the monoclonal Ab (mAb) NKG2A/CD94 complex on Vδ2 T cells or MHC class I molecules on target cells increases the cytotoxic response of Vδ2 T cells to HLA-E-expressing tumor cells." (PMID 36831606, 2023). "Combined, the LMP-1 GGDPHLPTL and HLA-E*0103/0103 variants efficiently inhibited NKG2A+ NK cells, thereby facilitating the in vitro spread of EBV-infected tumor cells." (PMID 37426645, 2023). "Recent studies reported that a variety of tumor cells highly expressed HLA-E, which allowed them to escape the immune recognition of NK and CD8+ T cells by interactions with inhibitory receptors of the CD94-NKG2 family." (PMID 36672208, 2023). "Tumor cells exploit this mechanism to evade the immune response, making it essential to block the interaction of HLA-E and NKG2A to enhance anti-tumor immune responses." (PMID 37103820, 2023). "For instance, HLA-E, overexpressed by tumor cells, represents an immune-suppressive feature by binding CD94/NKG2A, on NK and T cells." (PMID 36829496, 2023). "Overall, these results demonstrate that NKG2A is a functional IC in Vδ2 TILs and that the anti-tumor effector functions of NKG2A+ Vδ2 TILs are finely tuned by the degree of HLA-E expression on tumor target cells." (PMID 36831606, 2023). "NK‐cell reactivity against cancer is conceivably suppressed in the tumor microenvironment by the interaction of the inhibitory receptor NKG2A with the non‐classical MHC‐I molecules HLA‐E in humans or Qa‐1b in mice." (PMID 37782273, 2023). "CD155 and MICA/MICB values oscillated up and down, while HLA-E intensity remained unchanged in infected OvCa tumor digests." (PMID 37949944, 2023). "In vitro, the overexpression of HLA-E by tumor cells significantly inhibited wild-type (WT) NK cell cytotoxicity with p-values ranging from 0.0071 to 0.0473 depending on tumor cell lines." (PMID 37675109, 2023). "It has been demonstrated that monalizumab's efficacy strongly depends on HLA‐E expression on tumor cells." (PMID 37782273, 2023). "The expression of HLA-E on OC tumors is heterogenous; however, in one study of 270 OC patients, the HLA-E expression level in the tumor was higher compared to that in the normal epithelium in 89% of the cases." (PMID 37444472, 2023).
tumor (continued). "To reduce NKG2A expression and its engagement with HLA-E on tumor cells, we used a CRISPR/Cas system to target KLRC1, the gene encoding for NKG2A, in NKAES." (PMID 37675109, 2023). "constructed NKG2A-null NK cells in which NKG2A expression was abrogated and found that they had increased cytotoxicity against HLA-E-expressing tumor cells." (PMID 36960057, 2023). "An analysis of 10,375 human tumors, representing 33 tumor types, revealed that HLA-E is widely overexpressed by tumor cells." (PMID 37675109, 2023). "We did not explore the exact ligand of NK cells associated with functional assays, however, the results supported that surface HLA-E on tumor cells primarily recognized inhibitory receptors on NK cells." (PMID 38007483, 2023). "In the multivariate analysis, residual tumor, intratumoral CD3, and HLA-E on tumor cells were more predictive than other parameters." (PMID 35267497, 2022). "The interaction between NKG2A and HLA-E contributes to tumor immune escape, and NKG2A-mediated mechanisms are currently being exploited to develop potential antitumor therapeutic strategies." (PMID 36032104, 2022). "A precise understanding of the effect of these cytotoxic anti-cancer agents on NK cell viability/function directly, as well as on surface HLA-E kinetics and NK activating ligand expression on tumour cells will be required for optimal combination strategies." (PMID 36560403, 2022). "They further found NKG2Anull NK cells showed higher cytotoxic activity against HLA-E expressing tumor cells in immunodeficient mice." (PMID 36032104, 2022). "While classical MHC molecules are frequently lost by tumours to escape T cell control, various studies report high HLA‐E protein levels in cancer compared to healthy controls." (PMID 35596615, 2022). "NKG2A/CD94 heterodimer recognises non-classical HLA molecules and plays a key role in the tolerance of HLA-E+ tumours." (PMID 35806034, 2022). "Primary NK cells transduced with NKG2A siRNA have been shown to be more cytotoxic towards an HLA-E positive B lymphoblastoid cell line and in vivo adoptive transfer of NKG2A siRNA-transduced NKL cells enhanced clearance of HLA-E-positive 721.221 tumours." (PMID 36560403, 2022). "Concerning OS, residual tumor (HR = 2.19; 95% CI: [1.00; 13.30]) and HLA-E (HR = 0.23; 95% CI: [0.22; 1.00]) were the only two independent factors identified by the lasso model." (PMID 35267497, 2022). "Disruption of NKG2A:HLA-E interactions are therefore of great interest to promote anti-tumour immunity and multiple different strategies are in development to directly target this immune checkpoint." (PMID 36560403, 2022). "Normally, tumour cells expressing HLA‐E activate the KLRC1 receptor in cytotoxic lymphocytes and protect themselves from lysis." (PMID 35184420, 2022). "The results were consistent with our findings above that HLA-E was overexpressed on tumor cells and positively correlated with STK10 expression." (PMID 35501867, 2022). "HLA-E on tumour cells suppresses NKG2A-expressing NK and T cells in the tumour micro-environment and this can be reverted by blocking NKG2A." (PMID 36192118, 2022). "Among 98 assessable samples, 73.5% (n = 72) overexpressed HLA-E (scoring 2 and 3, called HLA-Ehigh) and 26.5% (n = 26) expressed normally or low HLA-E (scoring 0 and 1, called HLA-Elow) on tumor cells." (PMID 35267497, 2022). "When expressed on tumor cells, HLA-G and HLA-E were shown to interact with inhibitory receptors expressed on T cells and NK cells, negatively affecting cytotoxic functions of both CD8+ T cells and NK cells." (PMID 36612267, 2022). "Our study confirmed differential TME focusing on HLA-E expression on tumor cells between HRD and HRP HGSOC, which argues in favor of a need for a stratified strategy in future clinical trials." (PMID 35267497, 2022). "In turn, the overexpression of HLA-E was correlated with expression of tumour-infiltrating CD8+ T lymphocytes." (PMID 35073851, 2022).